CLDN1 (claudin 1)
Diseases named in the same sentence as CLDN1 in open-access papers (continued):
Sharing a sentence is not in itself a finding about the gene and the disease.
triple-negative breast carcinoma (10 papers, 2014 to 2026). An invasive breast carcinoma which is negative for expression of estrogen receptor (ER), progesterone receptor (PR), and human epidermal growth factor receptor 2 (HER2). "There is evidence that low CLDN1 expression is associated with a poor prognosis in patients with triple-negative breast cancer." (PMID 39457456, 2024). "Elevated DOCK1 expression enhances tumor cell migration via pathways involving RRP1B and Claudin-1, particularly in claudin-low and triple-negative breast cancer cells." (PMID 41516402, 2026). "In triple negative breast carcinoma, claudin 1 has been reported to be expressed in 44.5% of cases, compared with 5% in ER positive tumours." (PMID 31044387, 2020). "In triple-negative breast cancer (TNBC), the low expression of CLDN1-correlates with a high risk of recurrence and death." (PMID 26067567, 2015). "Additionally, CLDN1 overexpression increases the sensitivity of triple-negative breast cancer cell lines to the chemotherapeutic agents 5-fluorouracil, paclitaxel, and doxorubicin." (PMID 39457456, 2024). "Collectively, claudin-1 can both promote or suppress tumorigenesis, depending on the cancer type.MDA-MB-231, the cell line used in this study, is a basal B/triple-negative breast cancer (TNBC) cell line." (PMID 32309226, 2020). "The immunohistochemical expression of claudin 1, 3 and 4 was studied in 11 cases of in situ and invasive apocrine breast carcinoma, 7 benign apocrine lesions and 45 consecutive morphologically non-apocrine triple negative breast carcinomas." (PMID 31044387, 2020).
adenoma (9 papers, 2012 to 2024). A neoplasm arising from the epithelium. "Claudin-1 was identified as a promising target for early detection of CRC based on a 2.5 fold increase in gene expression in human adenomas versus normal colonic mucosa." (PMID 38337789, 2024). "Papillary thyroid cancer and thyroid adenoma showed positive expression of claudin-1, while claudin-4 was positive in papillary thyroid cancers, goiters, and adenomas." (PMID 39458944, 2024). "The presence of adenoma colonoids were localized using wide-field endoscopy, and claudin-1 expression by epithelial cells was visualized with sub-cellular resolution using dual axes confocal endomicroscopy." (PMID 38337789, 2024). "This peptide showed greater intensity for human adenomas, hyperplastic polyps and sessile serrated adenomas thus proposing the possibility of using claudin-1 peptide aided endoscopic imaging for the future clinical translation to detect precancerous lesions." (PMID 31861759, 2019). "Among the 52 matched samples, 45 samples with matched normal tissue, adenoma and adenocarcinoma were used to confirm CLDN1 overexpression by immunohistochemistry." (PMID 28659146, 2017). "CLDN1 staining was significantly higher in the adenoma and adenocarcinoma samples compared with the matched normal mucosa (p < 0.001)." (PMID 28659146, 2017). "CLDN1 was expressed in the cytoplasm in 87% of normal mucosa (39/45 patients) and in 40% of adenoma samples (18/45)." (PMID 28659146, 2017). "At least one of the two protein markers, claudin 1 or toll-like receptor 4, scored ≥4 in 83% of adenoma and adenocarcinoma samples in the CRC TMA." (PMID 26894861, 2016). "For CLDN1, 79% and 68% of adenoma and adenocarcinoma samples scored ≥4 respectively, and 0% of normal colon samples scored ≥4." (PMID 26894861, 2016). "Here we show that claudin-1 overexpression in APCMin mice induces mucosal permeability by inducing early adenoma formation." (PMID 24997475, 2014). "Claudin-1 was expressed in significantly higher levels in adenomas (p = 0.034) and adenocarcinomas (p = 0.005), comparing with normal epithelium." (PMID 22408413, 2012). "In our study, immunohistochemistry confirmed elevated expression level of claudin-1 both in adenomas, in particular adenomas with severe dysplasia, as well as in CRC, when compared to normal adjacent mucosa." (PMID 22408413, 2012). "Predominating strong positivity of claudin-1 was detected in tumor cells of adenocarcinomas and adenomas." (PMID 22408413, 2012). "In our cohort, claudin-1 and claudin-4 expression patterns were similar, with nearly uniform positive expression in papillary carcinomas, negative expression in undifferentiated and medullary carcinomas, and varied expression in adenomas." (PMID 39458944, 2024). "Positive claudin-1 expression was observed in 31% of adenomas (18/58) and 39% of cancers (16/42)." (PMID 39458944, 2024). "An IHC stain confirmed strong claudin-1 expression by adenoma colonoids." (PMID 38337789, 2024). "In our cohort, claudin-1 was positive in papillary carcinoma and, to a smaller degree, in adenomas." (PMID 39458944, 2024). "Adenomas are pre-malignant; thus, claudin-1 serves as an early target." (PMID 38337789, 2024). "Based on the pathology scores, CLDN1 and TLR4 were the only two marker proteins that effectively distinguished adenomas and adenocarcinomas from normal colon samples by this scoring method." (PMID 26894861, 2016). "CLDN1, GPR56 and LY6G6D/F had the broadest expression among adenoma samples with 79, 81 and 88% with pathology scores ≥4." (PMID 26894861, 2016). "Goiters, adenomas, and medullary and anaplastic cancers showed low or negative claudin-1 expression." (PMID 39458944, 2024). "At the RNA level, CLDN1 was found to be upregulated in adenomas compared to the normal colon (n = 42)." (PMID 38540693, 2024). "Goiter and adenoma samples showed low or no claudin-1 expression, suggesting the deregulation of the tight junction barrier." (PMID 39458944, 2024).
adenoma (continued). "While high claudin-1 expression is characteristic of papillary thyroid carcinoma, positive claudin-1 staining does not allow to distinguish benign pathologies, such as adenomas, from aggressive cancers, such as anaplastic thyroid cancer." (PMID 39458944, 2024). "Claudin-1 remained located on the cytoplasmic membranes mainly in adenomas without or with mild dysplasia, whereas the shift to the cytoplasm with cytoplasmic or membranous/cytoplasmic expression was observed in high-grade dysplastic adenomas and carcinomas." (PMID 22408413, 2012). "In tumor cells of adenocarcinomas and adenomas, prevailing strong positivity of claudin-1 was detected, without significant quantitative differences between the two groups." (PMID 22408413, 2012).
cervical cancer (9 papers, 2016 to 2025). A primary or metastatic malignant neoplasm involving the cervix. "Increased expression of CLDN1 in cervical cancer cells has been linked to increased resistance to apoptosis and invasive ability." (PMID 40687428, 2025). "To clarify whether CLDN1 protein expression has a causal role in tumor progression and invasion, we first tested the expression levels of CLDN1 in different cervical cancer cell lines." (PMID 27974683, 2016). "In summary, cervical cancer progression is marked by a dynamic modulation of claudins – with early lesions showing claudin overexpression and late-stage cancers showing claudin loss (for CLDN1,2,4,7), alongside sustained or newfound expression of other claudins (CLDN6,8,9) that promote metastasis." (PMID 40687428, 2025). "Expression of CLDN1/2/4/7 proteins has been reported to be increased in cervical cancer tissues, but the clinicopathological significance has yet to be defined." (PMID 33917356, 2021). "In contrast to claudin-1, claudin-6 is downregulated in cervical carcinoma, and expression of claudin-6 leads to decreased cell proliferation, colony formation in vitro, and tumor growth in vivo." (PMID 32197343, 2020). "Several studies exploring CLDN1 expression in patient material from cervical cancer has been reported recently, which were consistent with our data." (PMID 27974683, 2016). "CLDN1 has been detected at significantly increased levels in cervical cancer, compared to normal cervical epithelium, and has been implicated in cervical cancer progression." (PMID 26901676, 2016). "The expression of CLDN1 protein was significantly increased from normal cervical tissues to cervical cancer tissues." (PMID 27974683, 2016). "The expression of CLDN1 mRNA was firstly tested using reverse transcription PCR in 73 fresh cervical cancer tissues and 20 normal cervical tissues." (PMID 27974683, 2016). "We find that the copy number and protein expression of claudin-1 (CLDN1) increase with the progression of cervical cancer." (PMID 27974683, 2016). "The results showed that the expression of CLDN1 mRNA was increased significantly in cervical cancer tissues (p<0.05)." (PMID 27974683, 2016). "In conclusion, the copy number of CLDN1 was increased in cervical cancer, which might enhance cervical cancer cell anti-apotptosis ability and stimulate invasion and metastasis, mainly through EMT/invasion-related genes." (PMID 27974683, 2016). "In cervical cancer cells, CLDN1 overexpression could promote invasion and metastasis." (PMID 29221203, 2017). "Moreover, CLDN1 may be a potential prognostic marker and a candidate cell surface therapeutic target in cervical cancer." (PMID 27974683, 2016). "The copy number and protein expression of claudin-1, CLDN1, was found to increase with the progression of cervical cancer." (PMID 36232772, 2022). "Therefore, CLDN1 could be a potential therapeutic target for the treatment of cervical cancer." (PMID 27974683, 2016). "CLDN1 had a direct or an indirect interaction with SNAI1 in SiHa cells, which was demonstrated by immunoprecipitation; this result suggested that the consequence of overexpression of CLDN1 could increase the invasion of cervical cancer cells." (PMID 27974683, 2016).
Constipation (9 papers, 2015 to 2025). Infrequent or difficult evacuation of feces. "B. adolescentis significantly restores the suppressed expression of tight junction proteins ZO-1 and Claudin-1 in constipation models, suggesting it exerts its anti-constipation effects by repairing the integrity of the intestinal mucosal barrier." (PMID 41465567, 2025). "Among the three regulators, there was increased expression of Claudin-1 in the C3 KO model compared to the Lop-induced constipation model." (PMID 41011160, 2025). "The water extract of Cannabis sativa L. was found to significantly reverse the reduction in the expression of gut barrier-related molecules, including Claudin-1 and Occludin, at the mRNA level in constipation model mice." (PMID 40432966, 2025). "The expression levels of three TJ components, including occludin, ZO-1, and claudin-1, except claudin-4, were significantly recovered in the Lop-induced constipation rat model after treatment with phlorotannin (Pt)." (PMID 39857371, 2024). "Similarly, administration of L. plantarum T34 has been reported to alleviate loperamide-induced constipation by restoring the thickness of the colonic muscle layer and upregulating the expression of claudin-1 and MUC3, thereby enhancing mucosal barrier function." (PMID 41365536, 2025). "Also, other changes, such as increased ZO-1, decreased claudin-1, and no change in occludin, were detected in Lop-induced constipation mice after treatment with Wenyang Yiqi Decoction (WYD)." (PMID 39857371, 2024). "Compared with claudin-1 mRNA expression in the small intestine as well as the colonic mucosa of the control group, it was significantly decreased in diarrhea-predominant IBS (P<0.05), while it was significantly increased in constipation-predominant IBS (P<0.05)." (PMID 25998845, 2015).
dermatitis (9 papers, 2009 to 2024). An inflammatory process affecting the skin. "In addition, a dose-dependent association was found between Claudin-1 expression and the degree of skin inflammation, as well as a favorable correlation with skin barrier function." (PMID 39204346, 2024). "Topical application of a high concentration of glucose has been suggested to reduce skin inflammation and induce cldn-1 and filaggrin expression in inflamed skin." (PMID 36836073, 2023). "Epithelial-specific IL-33 transgenic mice have been found to develop AD-like dermatitis, including acanthosis, pruritus, increased IgE serum levels, reduced claudin-1 expression, and increased production of eosinophils, mast cells, and ILCs33,34." (PMID 32792500, 2020). "While claudin-1 knockout is lethal, low claudin-1-expressing conditioned mice exhibited AD-like dermatitis and an increased recruitment of neutrophil and macrophage in the skin." (PMID 27483258, 2016). "Th17 cells have been shown to infiltrate the skin lesions of AD, particularly during the acute phase of dermatitis, which suggested that IL-17 produced from Th17 cells decreases TJ function by inhibiting the synthesis of ZO-1, claudin-1, and claudin-4 proteins in AD." (PMID 27588419, 2016).
irritable bowel syndrome (9 papers, 2019 to 2025). Irritable bowel syndrome (IBS) is a chronic functional condition of the lower gastrointestinal (GI) tract characterized by abdominal pain or discomfort and disordered bowel habit (diarrhea, constipation, or fluctuation between the two). "For example, miRNA‐29a regulates intestinal barrier function in irritable bowel syndrome with diarrhea through the regulation of ZO‐1 and CLDN1." (PMID 37218372, 2023). "While we saw no changes in jejunal TJ protein expression, others have reported KD to increase the expression of small intestinal claudin-1 protein but not gene expression in conjunction with lowering inflammation and restoring crypt length in a rat model of irritable bowel syndrome." (PMID 38201850, 2023). "Another interesting miRNA is certainly miR-29 since its expression downregulates CLDN1 and NKRF, leading to increased intestinal permeability, as observed in studies on knockout mice and in tissue samples from patients with irritable bowel syndrome (IBS)." (PMID 39683426, 2024).
perineurioma (9 papers, 2011 to 2025). A usually benign perineurioma not associated with a nerve, arising from the soft tissues. "Claudin-1, a protein associated with tight junctions, is expressed by perineurial cells and has been reported to be a highly sensitive and specific marker for perineurium and soft tissue perineuriomas." (PMID 40225020, 2025). "Glut-1 and claudin-1 are rather sensitive perineural markers that should be added to the immunohistochemical panel in cases where perineurioma is considered." (PMID 39412332, 2024). "Positivity for markers such as epithelial membrane antigen (EMA), collagen IV, claudin-1, and glucose transporter 1 (GLUT-1) is commonly used to confirm the diagnosis of perineuriomas." (PMID 40225020, 2025). "Immunohistochemical (IHC) analysis confirmed these dual components: schwannoma/perineurioma hybrids were positive for S100 and SOX10 in schwannomatous regions, while perineuriomatous areas expressed EMA, Claudin-1, and GLUT-1." (PMID 40218204, 2025). "In the subgroup analysis, which included 50 cases where three markers (EMA, GLUT-1, and claudin-1) were used in all samples, the results showed that EMA was positive in 84%, GLUT-1 in 94%, and claudin-1 in 88% of GI perineuriomas." (PMID 40225020, 2025). "Neurofibroma and schwannoma are distinguished by their consistent expression of S100 and SOX10, while perineurioma lacks S100 expression and instead exhibits membranous staining with EMA, GLUT-1, and Claudin-1." (PMID 39410565, 2024). "It has been stated that virtually all perineuriomas express EMA,12,13 while they are also positive for claudin-1 in about 90% of the cases." (PMID 21437510, 2011). "Perineuriomas are typically immunoreactive for EMA, GLUT1, CD34, and claudin-1." (PMID 39925503, 2025). "Whereas schwannomas and epithelioid MNSTs that were diffusely Sox10-positive and apparently derived from Schwann cells were completely negative for claudin-1, perineuriomas and perineurial MNSTs showed moderate to strong claudin-1 positivity." (PMID 35622732, 2022). "Immunohistochemically, the neurofibroma component is positive for S100, SOX10, EMA, Claudin-1, and GLUT-1, while the perineurioma component does not express S100." (PMID 40218204, 2025). "Regardless of localization and morphologic subtypes, perineuriomas immunohistochemically are characterized by the expression of vimentin, EMA, Glut-1, and claudin-1." (PMID 39412332, 2024). "In hybrid perineurioma/schwannoma, Sox10 and GFAP expression was restricted to the part of the schwannoma, whereas the perineurioma regions expressed claudin-1 moderately to strongly and were negative for Sox10 and GFAP." (PMID 35622732, 2022). "Four MNSTs (6.0%) were strongly immunoreactive for claudin-1 and negative for Sox10 and GFAP and were accordingly classified as MNSTs with perineurial differentiation or malignant perineurioma." (PMID 35622732, 2022). "The result from immunophenotyping our case consisted of findings that typically occur in perineuriomas, i.e. strong expression of EMA and claudin-1 with no expression of S-100 protein." (PMID 21437510, 2011).
asthma (8 papers, 2014 to 2025). "Haptoglobin expression correlated negatively with asthma/rhinoconjunctivitis (β = −0.39, p = 0.05), and low 25(OH)D levels (<30 ng/mL) were associated with claudin-1 (β = −2.04, p = 0.0077) and occludin-1 (β = 0.43, p = 0.002)." (PMID 39796069, 2024). "Claudin-1 is confirmed to be closely associated with the disruption of epithelial structure in respiratory diseases and plays a key role in the pathological process of asthma." (PMID 39201796, 2024). "Our observations of lower expression of key junctional proteins, claudin-1, occludin, ZO-1, and e-cadherin, corroborate our earlier findings in children with mild asthma and suggest the airway epithelium in children with acute wheeze is inherently impaired." (PMID 40791985, 2025). "VEGF levels are also affected by claudin-1, whose elevated levels were observed in patients with asthma and a mouse model of asthma-like airway inflammation." (PMID 37174726, 2023). "Aside from the skin and GI tract, in the airway epithelium, claudin-1 expression level was negatively correlated with asthma severity, both in patients with asthma and in the house dust mite-induced mouse asthmatic model." (PMID 35844593, 2022). "We next evaluated dynamic changes of DSG1, E-cadherin and CLDN1, which are the main junction proteins of desmosome, AJ and TJ, respectively, in the airway during different phases of asthma recurrence model." (PMID 32076408, 2019). "CLDN1 knockdown in murine lungs significantly exacerbated the airway inflammation and the increased airway hyperreactivity in a mouse model of asthma, linking the claudin-1 downregulation directly to AA pathogenesis through the dysregulated airway barrier function." (PMID 35844593, 2022). "Neutrophil autophagy and neutrophil extracellular traps could enhance asthma severity by inducing claudin-1 degradation." (PMID 35844593, 2022). "Moreover, MMP-9 alters the localization of tight junction components, such as claudin-1, occludin, and ZO-1, adversely affecting barrier function and eventually directly damaging respiratory epithelium in asthma." (PMID 24533168, 2014). "Similar to our data in asthma, a recent study indicates that in a piglet model of intestinal injury, pretreatment with Nec-1 inhibited LPS-induced necroptosis, improved the reduced expression of jejunal tight junction proteins claudin-1 and occludin protein, and ameliorated barrier function." (PMID 38987753, 2024). "To verify this hypothesis, we observed the dynamic changes of CLDN1, E-cadherin and DSG1 in lung tissue in different phases of asthma recurrence model, especially during the remission period." (PMID 32076408, 2019).